IFNG (interferon gamma)
Diseases named in the same sentence as IFNG in open-access papers (continued):
Sharing a sentence is not in itself a finding about the gene and the disease.
tumor (continued). "IFNγ, also called type II interferon or immune interferon, is mainly produced by activated T cells and NK cells, and acts as an important mediator of the immune system, involving activities such as immuno-modulation, lymphocyte recruitment and activation, anti-pathogen and anti-tumor activity." (PMID 19948041, 2009). "To test the hypothesis that the more potent tumor eradication in mice receiving P14IL-2 (0 h) effector cells is caused by greater cytolytic function of the cells transferred, we checked the production of granzyme B and IFNγ of the tumor-infiltrating lymphocytes of effector cells." (PMID 19901991, 2009). "However, recent studies show that CD4 helper T cells, secreting IFNγ, may play an important role in tumour rejection as well." (PMID 18728665, 2008). "However, tumor cells are able to escape from the control of this cytokine in the early tumor stages; this could be due to a decreased expression of IFNγ, or also to an alteration of either its receptors." (PMID 17697357, 2007). "Analysis of TGCT cell lines demonstrated that they expressed and secreted IFNγ, but were resistant to the endogenous IFNγ since neutralisation of IFNγ by a specific blocking antibody had no influence on the proliferation and/or the degree of apoptosis of tumour cells." (PMID 12942126, 2003). "In addition, FA-CS-R848/DOX@Lip increased the MHC II/CD206 ratio of tumor-associated macrophages (TAMs), elevated the proportions of CD8+ and CD4+ T cells, reduced the proportion of myeloid-derived suppressor cells (MDSCs), and enhanced the percentages of IFNγ+ and Ki67+ CD8+ T cells in vivo." (PMID 42220424, 2026). "NK cells do this through direct lysis of CSCs or by releasing cytokines like interferon-gamma (IFN-γ) and tumor necrosis factor-alpha (TNF-α), which inhibit tumor growth and metastasis by driving differentiation of CSCs." (PMID 41898674, 2026). "Type 1: immune cold with stroma-restricted CD8+ T cell secretion of interferon gamma, which activates COX2 expression at the tumor margin as well as NOS2 expression at the tumor periphery." (PMID 42097035, 2026). "A study found that immune checkpoint inhibitors activate and induce CD8+ T cells to secrete interferon‐gamma (IFN‐γ), which negatively regulates the expression of the Xc system components SLC3A2 and SLC7A11 on the surface of tumor cells." (PMID 41560416, 2026). "This upregulation, in the presence of Interferon-gamma (IFN-γ), facilitates the polarization of anti-tumor macrophages." (PMID 41522342, 2026). "Although H3B-120 treatment initially reduced the activity of tumor-infiltrating cytotoxic CD8+ T cells, as measured by IFNγ levels, the addition of anti-PD-1 antibody restored this activity." (PMID 41356199, 2026). "The expression of T cell activation markers (CD25 and CD69), as well as anti-tumor cytokines (GZMB, IFNγ, and PRF1), was significantly suppressed when incubated with the supernatants of NAC-pre-treated neutrophils." (PMID 41516400, 2026). "The resultant lowering of intracellular cholesterol allowed better T cell activation, as well as IFNγ and GZMB production, ultimately leading to a retardation of tumor growth." (PMID 41557725, 2026). "The levels of CD4+ and CD8+ tumor‐infiltrating lymphocytes, as well as CD8+ T cell effector molecules IFNγ and GZMB, within the TME also dramatically increased in tumor‐bearing mice with dual‐drug therapy treatment." (PMID 40344511, 2025). "Intracellular flow cytometry analysis of the effector cytokines IFNγ and TNF, which have direct anti-tumor properties, showed a significant increase in IFNγ and TNF expression by NK cells upon treatment with 8H8_SDIE." (PMID 40821788, 2025). "In contrast, γδ TILs not only significantly increased CD107a expression when exposed to tumor digest (P = 0.008), but also substantially increased the production of TNF and IFNγ (TNF: P = 0.03; IFNγ: P = 0.008)." (PMID 40897471, 2025).
tumor (continued). "In tumor immunity, CD4+ Tem cells directly kill cancer cells, destroy tumor vasculature, and maintain leukocyte responses by secreting cytokines such as IFNγ and TNF." (PMID 40801655, 2025). "CAR-NK cells also secrete proinflammatory cytokines such as interferon-gamma (IFN-γ) and tumor necrosis factor-alpha (TNF-α), which not only contribute to direct tumor control but also modulate the tumor microenvironment (TME) to enhance antitumor immunity." (PMID 40723278, 2025). "Strikingly, A1R but not A3R CAR T cells produced significantly higher levels of both IFNγ and TNF when cocultured with either tumor cell line." (PMID 40610421, 2025). "IFNγ can facilitate CD8+ T cell priming and infiltration by upregulating the expression of B2M/MHC-I on the surface of tumor cells." (PMID 40191187, 2025). "Hewitt and scientists from Moderna reported that a single IT dose of LNPs encapsulating mouse mIL12 mRNA induced IFNγ and CD8 T-cell–dependent tumor regression in multiple syngeneic mouse models and exhibited abscopal effects." (PMID 40006725, 2025). "Although o22R produced moderate levels of cytotoxicity transcripts, flow cytometry revealed high densities of intratumoural IFNγ+TNF+ and GZMB+ cells, consistent with superior anti-tumour activity of o22R." (PMID 40804519, 2025). "A CRISPR screen has identified genes involved in IFNγ and TNFα signaling as critical mediators of CD8+ T cell‐mediated tumor cell killing." (PMID 40178291, 2025). "Systemic administrationof CpG@MSN-PEG/PEI@OMVs effectively suppressed tumor growth and preventedlung metastasis primarily by promoting APC maturation, inducing M1macrophage polarization, and activating IFNγ-secreting CD4+ and CD8+ T lymphocytes." (PMID 40392526, 2025). "IFNγ secreted by Th1 cells can reprogram TAMs toward an M1 phenotype by activating the JAK–STAT1 signaling pathway, thereby enhancing anti-tumor immune responses." (PMID 41019045, 2025). "In murine models, IFNγ treatment enhances NET formation and apoptosis, reduces tumor burden, and strengthens PD-1 antibody–mediated tumor cytotoxicity in MSS CRC cell lines." (PMID 41320679, 2025). "The roles of MHC-I, including HLA-A/B/C, are well-established in tumor biology, where IFNγ, secreted by tumor-infiltrating T cells, can induce expression of MHC-I on tumor cells and boost CD8+ T cells cytotoxicity." (PMID 41162356, 2025). "This process promotes the induction of certain cytotoxic cytokines, such as interferon-gamma (IFNg) and transforming growth factor-beta (TGF-β), leading to enhanced T cell-mediated immune response against tumor cells." (PMID 40565299, 2025). "Th1 CD4+ T-cells release pro-inflammatory signals, such as interferon-gamma (IFN-γ) and interleukin-2 (IL-2), which lead to the maturation of APCs and thus enhanced tumor antigen presentation to CD8+ T-cells." (PMID 40362529, 2025). "These approaches have led to increased interferon-gamma (IFN-γ) levels and infiltration of CD8+ T cells, resulting in tumor suppression in HCC models." (PMID 41300975, 2025). "M1 macrophages, activated by pro-inflammatory signals like interferon-gamma (IFN-γ), IL-1β, and IL-12, exhibit anti-tumor activity by enhancing cytotoxic T-cell responses and directly killing tumor cells." (PMID 40565133, 2025). "SCFAs also enhance IFNγ-mediated responses and T cell differentiation, contributing to stronger CD8+ T cell mediated tumor clearance." (PMID 40422211, 2025). "The data also argue that any competition between the FAP8-FL and folate-FL for binding to the anti-FL CAR must be minimal, since tumor eradication, CAR T cell infiltration, and IFNγ release all improved by concurrent administration of the two adapters." (PMID 40034702, 2025). "ho22R enhanced CAR T cell enrichment in tumours, where they exhibited reduced exhaustion (lower PD-1 and LAG3), and maintained IFNγ and GZMB secretion." (PMID 40804519, 2025).
tumor (continued). "The remodeling of tumor blood vessels and anti-angiogenic effects of anti-CTLA-4 antibodies require the presence of CD4+ T cells and the activity of IFNγ, a potent anti-angiogenic cytokine." (PMID 40460830, 2025). "It exerts anticancer efficacy by enhancing the tumor microenvironment and improving the infiltration of human CD8+ T-cells and the release of human IFNγ in tumor tissue." (PMID 40422248, 2025). "Flow cytometric analysis revealed more cytotoxic CD8+ T-cells with higher IFNγ, TNFα, and IL2 expression—indicative of a more effective anti-tumor immune response (SF." (PMID 40951290, 2025). "Pharmacological targeting of TPC2 with SG094 increased IFNγ secretion in CD8+ T cells, both alone and in tumour co-culture settings, and further elevated cytokine release when combined with immune checkpoint inhibitors." (PMID 41209002, 2025). "Functionally, the combination treatment led to a significant increase in IFNγ+CD8+ T cells, further supporting the anti-tumor immune reprogramming of the TME of HCC induced by this therapeutic approach." (PMID 40321752, 2025). "IFNG and IFNGR1 are upstream regulators of STAT1, and the binding of IFNG to IFNGR1 activates STAT1, exerting anti-tumor effects." (PMID 40659662, 2025). "Flow cytometry analysis of CD4+ Tumor-Infiltrating Lymphocytes (TILs) and draining lymph nodes from B16F10 tumor-bearing mice revealed increased IFNγ production in CD4Nlrp3-/- mice compared with control mice at both the mRNA and protein levels." (PMID 40195474, 2025). "M1-like TAM programming then facilitated the recruitment and activation of IFNγ+CD8+ T cells that, in turn, enforced IFNγ-dependent M1-like TAM polarization to inhibit tumor growth." (PMID 40475851, 2025). "GSEA based on RNA-seq further revealed that a robust IFNG and TNFA responses within the TNBC tumour microenvironment following posaconazole treatment." (PMID 40287432, 2025). "In vivo experiments demonstrated that BN1 effectively reduced tumor burden while exhibiting immunostimulatory effects, including the increase of CD8+ IFNγ+ cells, the decrease of CD4+ Foxp3+ cells, and the regulation of cytokines." (PMID 40885393, 2025). "Our study highlights the potential of IFNG, KEAP1, and PHKG2 as predictive markers for T cell infiltration and the tumor microenvironment status in OV." (PMID 40744688, 2025). "Activation of anti-tumor immune response by effector CD8+ T-cells and increased IFNγ levels have been shown to promote the expression of HLA-E, the human orthologue of mouse Qa-1b, in tumor cells." (PMID 39706891, 2025). "Inhibited EMT markers, boosted IFNγ+ CD8+ T-cells 4.4-fold, reduced tumor size, and improved survival." (PMID 40918451, 2025). "SECTM1 is upregulated by IFN-γ (interferon-gamma)/STAT1 (signal transducer and activator of transcription 1) signaling in immuno-hot tumors, further highlighting its role in tumor-immune interactions." (PMID 40362379, 2025). "The expression of T cell activation receptor IL2R, along with various anti-tumor secretory factors (GZMB, IFNγ) and the inflammatory cytokine IL2, showed strong correlation with intracellular NAD+ levels." (PMID 40846839, 2025). "We found that the radiomic signature was significantly negatively correlated with tumor‐infiltrating CD8+ T cells, IFNγ signaling, and CE9/CE10 abundance." (PMID 39840456, 2025). "The expression of tsMHC‐II is commonly induced via interferon‐gamma (IFN‐γ) signalling through the STAT1–CIITA pathway, enhancing tumour immunogenicity." (PMID 40673641, 2025). "Specifically, the CXCL1, IFNG, and SERPINE1 in the tumor group had higher expression, while PIM1 and STK40 in the tumor group had lower expression." (PMID 40455337, 2025). "Their analysis demonstrated the expression of several chemokines such as IFNG and CXCL10, in tumor fragments from patients who responded clinically to ICB, irrespective of cancer type." (PMID 41432764, 2025).
tumor (continued). "Interferon-gamma (IFN-γ) regulates the expression of SLC3A2, SLC7A11, and ACSL4, subsequently inducing immunogenic ferroptosis in tumor cells." (PMID 40260246, 2025). "Specifically, an increase in the density of TILs (i.e., CD8+ T cells) and CXCL9 and CXCL10, which activate T cells and IFNg secretion from effector T cells, would demonstrate conversion of an HCC tumor into the hot phenotype." (PMID 41012682, 2025). "Cytotoxic/effector genes (GNLY, GZMA, GZMK, IFNG, NKG7, PRF1) were primarily expressed by T and NK cells, with notable upregulation in stRNA‐seq‐defined invasive front and tumor core regions." (PMID 41057994, 2025). "In this analysis, we found that cytotoxic CD4+ T cells largely correlated with reduced tumor growth in the triple therapy group, with the smallest tumors having the highest frequencies of CD4+ T cells with higher IFNγ and TNFα expression." (PMID 41171165, 2025). "Our study shows that increasing intracellular IFNG levels can induce ICD, enhancing immune cell recognition and killing of tumor cells." (PMID 39945555, 2025). "We found that CD4+ T, CD8+ T, proliferating T cells (T-pro), and NK cells activated the anti-tumor function of TANs through TNF and IFNG, including cytotoxicity, cytokine production, chemotaxis, migration and IFNγ signaling." (PMID 40360503, 2025). "This was accompanied by reduced infiltration of IFNγ+ and TNF+ CD8+ T cells and proliferating Ki67+ effector T cells within tumours of TAK-242-treated animals without significant effects on other immune cell populations." (PMID 39929976, 2025). "After ACT, inflammatory monocytes strongly expanded, especially in NTT tumours and RTTPtgs2 KO tumours, which suggested that both cancer-cell-derived IFN-I cytokines and T cell-derived IFNγ play a part in inducing the inflammatory state." (PMID 39604727, 2025). "Through the secretion of pro-inflammatory cytokines such as IL-12 and interferon-gamma (IFN-γ), neutrophils promote the activation of CTLs and natural killer (NK) cells, which are directly involved in recognizing and eliminating tumor cells." (PMID 40227814, 2025). "Immunotyping of single cells isolated from EG7 tumor tissues revealed that I3A treatment led to a significant rise in the frequency of tumor‐infiltrating CD8+ T cells, and the proportion of IFNγ expression on tumor‐infiltrated CD8+ T cells." (PMID 40583248, 2025). "B cells, through the production of IFNγ and IL-12p40, also contribute to the recruitment and activation of CD8+ T cells, further enhancing tumor control." (PMID 40308809, 2025). "Among Th subsets, Th1 cells mediate cytotoxicity via interferon-gamma (IFN-γ), while Th2 and Th17 cells, through IL-4, IL-13, and IL-17, support tumor progression." (PMID 41383623, 2025). "Interferon-gamma (IFN-γ) is secreted by activated T cells and NK cells, playing a crucial role in tumor progression through bidirectional regulation of immune responses." (PMID 41155287, 2025). "To investigate if TA33.Combo enabled the generation of tumor-specific CD8+ T cells, we performed an IFNγ ELISPOT assay on CD8+ T cells purified from the spleen of either control untreated or TA33.Combo-treated mice." (PMID 40216735, 2025). "Consistent with the slower tumor growth in the triple therapy + LC cohort, we measured increased cytotoxic CD4+GrB+, CD4+, and CD8+ IFNγ+TNFα+ and a trend to more memory T cells and fewer CD8+ regulatory T cells (Tregs) in the tumors." (PMID 41171165, 2025). "TC tumor cells expressed receptors for multiple signaling pathways, including MK, PTN, SPP1, TWEAK, EGF, and IFN-II (IFNG) (blue frames)." (PMID 41228323, 2025). "This can be argued as the presence of IFNγ that, according to our model, plays a dual role of (a) enabling the cytotoxic T cell to recognize the PDL1- tumor cells and (b) induce PDL1 expression on the tumor cells that can aid in the immune escape." (PMID 40460357, 2025).
tumor (continued). "Specifically, IL-11 activates STAT3 phosphorylation, which inhibits IFNγ-induced STAT1 phosphorylation, thereby downregulating MHC-I and CXCL9 expression in tumor cells and impairing CD8+ T cell infiltration—promoting immune evasion and tumor growth in CRC." (PMID 41359051, 2025). "For both HG-T and the other MT-HGs, patients with CB tended to have higher levels of each tested tumor marker (PD-L1, TMB, IFNγ/CD8+ immune infiltration)." (PMID 40473950, 2025). "PD1 is highly expressed in TAMs in response to IFNγ, MYD88/IL1R signaling and TLR2/3 stimulation, inhibiting the phagocytic capacity of M1 phenotype TAMS and impairing their ability to clear tumor cells." (PMID 41177809, 2025). "We found a significant increase of murine IFNγ (mIFNγ) and murine MCP-1 (mMCP-1) secretion after co-incubation of NK-92/5.28.z cells with tumor cells in the insert." (PMID 40102596, 2025). "These tumor-infiltrating Tregs suppress the expansion of effector CD4+ and CD8+ T cells and their secretion of interferon gamma (IFNγ)." (PMID 40399946, 2025). "Our results identify an intricate interplay between the Fc effector function of anti-CTLA-4 antibodies, IFNγ-producing effector CD4+ T cells, and tumor endothelial cells." (PMID 40460830, 2025). "Gene-modified cell therapy: IFNγ/sPD1-engineered BMSCs target lung adenocarcinomas, simultaneously suppressing PI3K/AKT, reducing Tregs by 40%, and inducing tumor senescence via p16 upregulation." (PMID 40781676, 2025). "In this model, serine/glycine deprivation significantly reduced tumor-reactive T cell cytotoxic activity and the expression of key T cell effector cytokines, including IL-2, TNF, and IFNγ." (PMID 40389477, 2025). "The Th1 subtype of CD4+ T cells (Th cells) can produce interferon gamma (IFNγ) and TNF-α to directly kill cancer cells and can exert anti-tumor effects by aiding B cells and CD8+ cells." (PMID 41001032, 2025). "The drug causes T-cells to become more active and leads to greater levels of interferon-gamma (IFN-γ) and tumor necrosis factor-alpha (TNF-a) in the tumor microenvironment." (PMID 40004731, 2025). "HSV-1 OV-mOX40L activated CD4 and CD8 T cells, as evidenced by increased IFNγ and granzyme b production, and increased migration of immune cells into the TME, similar to our observations with the UN-KC-6141 tumor model." (PMID 40430543, 2025). "Interferon-gamma (IFN-γ), a multifunctional cytokine secreted by activated immune cells in the inflamed tumor microenvironment, serves as a key regulator of MHC-I expression." (PMID 40849659, 2025). "Pretreating the tumor cells with BRQ increased levels of CD69, IFNγ, CD107a, and granzyme B expression in co-cultured CD8+ T cells, consistent with higher levels of cytotoxicity." (PMID 41339932, 2025). "One strategy involves using cytokines, such as interferon-gamma (IFN-γ), which can polarize neutrophils toward an anti-tumor phenotype." (PMID 40486614, 2025). "Lactobacillaceae delays tumor development by increasing the NK and CD8+ T-cell infiltration and increasing IFNγ production in the cancer microenvironment." (PMID 40431182, 2025). "While CD4+ T cells secrete interferon-gamma (IFNγ), a pro-inflammatory cytokine, to recruit more T cells, CD8+ T cells often become dysfunctional due to prolonged exposure to tumor antigens." (PMID 39859381, 2025). "IFNγ produced by CD8+ T cells triggers the JAK/STAT1 pathway, downregulating SLC7A11 and SLC3A2, which makes tumor cells more vulnerable to ferroptosis." (PMID 40136510, 2025). "In this context, our in vivo experiments have demonstrated that targeting the CMA translocase enzyme LAMP2A inhibits the degradation of STING and TBK1, enhancing the infiltration of IFNγ+CD8+ T cells and thus improving the "cold" tumor state." (PMID 40083918, 2025).